NDFIP2 (Nedd4 family interacting protein 2)
Description:
Activates HECT domain-containing E3 ubiquitin-protein ligases, including ITCH, NEDD4, NEDD4L, SMURF2, WWP1 and WWP2, and consequently modulates the stability of their targets. As a result, may control many cellular processes. Recruits ITCH, NEDD4 and SMURF2 to endosomal membranes. Negatively regulates KCNH2 potassium channel activity by decreasing its cell-surface expression and interfering with channel maturation through recruitment of NEDD4L to the Golgi apparatus and multivesicular body where it mediates KCNH2 degradation. May modulate EGFR signaling. Together with NDFIP1, limits the cytokine signaling and expansion of effector Th2 T-cells by promoting degradation of JAK1, probably by ITCH- and NEDD4L-mediated ubiquitination (By similarity).
Synonyms: KIAA1165; N4WBP5A
Tractability: Antibody: UniProt places it where antibodies can reach, with high confidence; UniProt predicts a signal peptide or a membrane-spanning region. PROTAC: UniProt records ubiquitination sites on it; ubiquitination databases record sites on it; its protein half-life has been measured.
Gene: Protein-coding gene on chromosome 13 (79,481,155 to 79,556,077, forward strand). Ensembl gene ENSG00000102471.
Subcellular location: Endosome membrane; Golgi apparatus membrane; Endosome, multivesicular body membrane
Subcellular location (Human Protein Atlas): Vesicles
Gene Ontology:
Molecular function: protein binding; WW domain binding
Biological process: positive regulation of canonical NF-kappaB signal transduction; proteasome-mediated ubiquitin-dependent protein catabolic process; positive regulation of protein ubiquitination; ubiquitin-dependent protein catabolic process; metal ion transport; vacuolar transport
Cellular component: cytoplasm; endoplasmic reticulum; endosome membrane; Golgi apparatus; Golgi membrane; mitochondrion; perinuclear region of cytoplasm; multivesicular body membrane
Genetic constraint (gnomAD): Loss-of-function variants: 16 observed, 23.69 expected, observed/expected ratio (o/e) 0.68, 90% interval 0.46 to 1.03. The upper end of that interval is the gene's LOEUF score, 1.03, which puts it in group 4 of 6, group 1 being the genes least tolerant of losing a copy. Missense variants: 399 observed, 342.43 expected, observed/expected ratio (o/e) 1.17, 90% interval 1.07 to 1.27. Synonymous variants: 161 observed, 128.94 expected, observed/expected ratio (o/e) 1.25, 90% interval 1.1 to 1.42.
Homologues: Orthologues: chimpanzee NDFIP2 (99% identical), macaque NDFIP2 (90% identical), pig NDFIP2 (86% identical), dog NDFIP2 (85% identical), rat Ndfip2 (84% identical), mouse Ndfip2 (83% identical), rabbit NDFIP2 (75% identical), tropical clawed frog ndfip2 (56% identical), guinea pig NDFIP2 (51% identical), zebrafish ndfip2 (51% identical), Drosophila melanogaster Ndfip (23% identical). Paralogues in human: NDFIP1 (40% identical).
Diseases named in the same sentence as NDFIP2 in open-access papers:
NDFIP2 is named in the same sentence as 18 diseases in open-access papers, as found by Europe PMC text mining. Sharing a sentence is not in itself a finding about the gene and the disease. The quoted sentences say what the papers report.
hepatocellular carcinoma (3 papers, 2022 to 2023). A malignant tumor that arises from hepatocytes. "In hepatocellular carcinoma (HCC), Gly-tRF targets Nedd4 family interacting protein 2 (NDFIP2) to promote the growth of HCC cells." (PMID 35658952, 2022). "In gastric cancer (GC) tRF-24-V29K9UV3IU and tRF-3019a inhibit tumor cell migration and invasion and promote apoptosis, while in hepatocellular carcinoma, Gly-tRF promotes cell migration and epithelial to mesenchymal transition (EMT) by binding to the 3′UTR of NDFIP2 mRNA." (PMID 36964534, 2023).
Hypertension (1 paper, 2017). The presence of chronic increased pressure in the systemic arterial system. "Furthermore, the expression of NDFIP2 in these segments, which also express its interacting partner ENaC, is consistent with the identification that a single nucleotide polymorphism in NDFIP2 correlates with hypertension." (PMID 28931009, 2017).
viral infection (1 paper, 2023). "As such, NDFIP2 levels may represent a fine-tuning step in the regulation of the steady-state levels of IFITM3, leading to dynamic changes in the cell susceptibility to viral infection." (PMID 37896772, 2023). "Given that the genetic removal of NDFIP2 in A549 cells resulted in a decrease in the steady-state levels of IFITM3, we sought to determine whether this translated into a higher susceptibility of these cells to viral infection." (PMID 37896772, 2023).
cancer (3 papers, 2021 to 2022). A tumor composed of atypical neoplastic, often pleomorphic cells that invade other tissues. "Collectively, these functional reversal experiments further confirmed that Gly-tRF acts as a cancer-promotor by targeting NDFIP2." (PMID 34537070, 2021). "Indeed, downregulation of ENTREP is seen in various types of cancer, whereas NDFIP1, NDFIP2, and N4BP1 are infrequently downregulated (Fig EV4A)." (PMID 34927784, 2022).
tumor (3 papers, 2021 to 2025). "Overexpression of NDFIP2 weakened the tumour-promoting effect of Gly-tRF on HCC cells and restored the level of phosphorylated AKT." (PMID 34537070, 2021). "Immunohistochemistry was used to verify the expression of NDFIP2 in HCC, and the results showed that 58/84 (69%) of the samples had lower NDFIP2 expression in tumour tissues than in non-tumor tissues." (PMID 34537070, 2021). "NDFIP2 is a direct target of Gly-tRF, and the overexpression of NDFIP2 modulates the AKT signaling pathway, thereby inhibiting the promoting effect of Gly-tRF on tumor metastasis." (PMID 40265011, 2025).
infection (1 paper, 2023). The state of being infected such as from the introduction of a foreign agent such as serum, vaccine, antigenic substance or organism. "As a result, A549 cells, in which NDFIP2 has been genetically removed by CRISPR/Cas9, exhibit lower levels of IFITM3 and become highly susceptible to infection." (PMID 37896772, 2023). "Despite the fact that NDFIP2 can exert additional effects on the virus life cycle, these results along with the decreased levels of accumulation of IFITM3 support the hypothesis that NDFIP2 at least partly regulates the cell susceptibility to infection via its role in IFITM3." (PMID 37896772, 2023).
psychiatric disease (1 paper, 2014). "As for the psychiatric disease variants we identified as targets of Δphotoperiod-driven selection, the two for MDD show different patterns: the risk allele frequency increases with Δphotoperiod for GPHN and decreases for NDFIP2/SPRY2." (PMID 25358694, 2014).
NDFIP2 also shares sentences with these, for which no sentence is quoted: acute myeloid leukemia (1 paper); bipolar disorder (1); breast carcinoma (1); colitis (1); gastric cancer (1); leukemia (1); macroglossia (1); memory impairment (1); multiple myeloma (1); myeloid neoplasm (1); schizophrenia (1).